RCOR2 (REST corepressor 2)
Description:
May act as a component of a corepressor complex that represses transcription.
Tractability: PROTAC: UniProt records ubiquitination sites on it; ubiquitination databases record sites on it; its protein half-life has been measured.
Gene: Protein-coding gene on chromosome 11 (63,911,220 to 63,919,787, reverse strand). Ensembl gene ENSG00000167771.
Subcellular location: Nucleus
Subcellular location (Human Protein Atlas): Nucleoplasm; Midbody; Vesicles
Gene Ontology:
Molecular function: protein binding; transcription corepressor activity; enzyme binding
Biological process: negative regulation of DNA-templated transcription; regulation of transcription by RNA polymerase II
Cellular component: histone deacetylase complex; transcription regulator complex; nucleus
Genetic constraint (gnomAD): Loss-of-function variants: 21 observed, 56.09 expected, observed/expected ratio (o/e) 0.37, 90% interval 0.26 to 0.54. The upper end of that interval is the gene's LOEUF score, 0.54, which puts it in group 2 of 6, group 1 being the genes least tolerant of losing a copy. Missense variants: 515 observed, 619.43 expected, observed/expected ratio (o/e) 0.83, 90% interval 0.77 to 0.89. Synonymous variants: 250 observed, 242.38 expected, observed/expected ratio (o/e) 1.03, 90% interval 0.93 to 1.14.
Homologues: Orthologues: macaque RCOR2 (99% identical), mouse Rcor2 (98% identical), pig RCOR2 (98% identical), rat Rcor2 (98% identical), dog RCOR2 (97% identical), guinea pig RCOR2 (97% identical), rabbit RCOR2 (86% identical), tropical clawed frog rcor2 (62% identical), zebrafish rcor2 (60% identical), chimpanzee RCOR2 (59% identical), Drosophila melanogaster CoRest (39% identical), Caenorhabditis elegans F28F8.7 (12% identical), and 3 more. Paralogues in human: RCOR3 (58% identical), RCOR1 (44% identical), MIDEAS (18% identical), TRERF1 (17% identical), ZNF541 (17% identical).
Diseases named in the same sentence as RCOR2 in open-access papers:
RCOR2 is named in the same sentence as 15 diseases in open-access papers, as found by Europe PMC text mining. Sharing a sentence is not in itself a finding about the gene and the disease. The quoted sentences say what the papers report.
breast carcinoma (5 papers, 2019 to 2025). "Kaplan-Meier analysis of the TCGA cohort revealed that high levels of RCOR2 were significantly associated with worse disease-free interval and progression-free interval in breast cancer patients." (PMID 40608411, 2025). "Nevertheless, we identify activation of Wnt/β-catenin signaling as the mechanism of RCOR2-induced breast cancer stemness and tumor initiation, which offers mechanistic insights into RCOR2-dependent stem cell biology." (PMID 40608411, 2025). "Consistently, we show that RCOR2 is negatively associated with MHC-II molecules in tumors and survival of breast cancer patients." (PMID 40608411, 2025). "We show a partial rescue effect of RNF43 silencing or CHIR99021 treatment on stemness of RCOR2-null breast cancer cells, although β-catenin activity is fully restored by these two interventions." (PMID 40608411, 2025). "Immunohistochemistry (IHC) analysis further confirmed increased infiltration of CD4+ and CD8+ T cells in RCOR2-KO PyMT mammary tumors compared with wild-type tumors." (PMID 40608411, 2025). "RCOR2 protein upregulation was confirmed in murine MMTV-PyMT mammary tumors and human triple-negative breast cancer." (PMID 40608411, 2025). "Homozygous deletion of Rcor2 significantly inhibited PyMT mammary tumor growth in mice." (PMID 40608411, 2025). "To validate the results from the genetically modified mammary tumor mouse model, we conducted allograft experiments by implanting parental and RCOR2-knockout (KO) murine tumor cells into the mammary fat pad of female BALB/c mice or the flank of male C57BL/6J mice." (PMID 40608411, 2025). "Expression of two potential downstream effectors of SOX11 signalling we recently identified in breast cancers cells, Mex3a and Rcor2, which have links to stem cell proliferation and reprogramming, respectively, were also substantially reduced in Brca1.3 cells with reduced Sox11 levels." (PMID 33969421, 2021). "Together, these findings indicate that RCOR2 enhances Wnt/β-catenin activation by RNF43 silencing, leading to increased breast cancer plasticity." (PMID 40608411, 2025). "To validate the role of RCOR2 in cancer cell plasticity observed in a murine mammary tumor model, we generated BCSC-enriched mammospheres from human breast cancer cells." (PMID 40608411, 2025). "To determine a role of RCOR2 in tumor progression, we crossed Rcor2-floxed mice with K14-Cre and MMTV-PyMT transgenic mice and monitored mammary tumor growth in mice over 5 months." (PMID 40608411, 2025). "Our present studies show that RCOR2 increases breast cancer stemness, suggesting a conserved function of RCOR2 from normal stem cells to cancer stem cells." (PMID 40608411, 2025). "We further confirmed that RCOR2 KO1 or KO2 did not inhibit human tumor growth in NSG mice orthotopically implanted with 2 million human MDA-MB-231 breast cancer cells." (PMID 40608411, 2025). "Moreover, RCOR2 replaces the need for Sox2 expression in somatic cell reprogramming, whereas Sox2 has a positive expression in the basal-like subtype, although it has not been directly related to the breast cancer subtype." (PMID 31296201, 2019).
acute myeloid leukemia (1 paper, 2025). Acute myeloid leukemia (AML) is a group of neoplasms arising from precursor cells committed to the myeloid cell-line differentiation. "In acute myeloid leukemia (AML), RCOR2 was found to be upregulated in B7-H4-null cells, and its knockdown resulted in reduced leukemogenesis." (PMID 40936699, 2025).
breast tumor (1 paper, 2025). "We next examined whether RNF43 silencing contributes to RCOR2-induced breast tumor plasticity." (PMID 40608411, 2025). "Interestingly, breast tumor cell plasticity induced by RCOR2 is LSD1 dependent." (PMID 40608411, 2025).
disc degeneration (1 paper, 2025). "In severe disc degeneration, RCOR2, STAT3, NOTCH1, SP1, and SART1 expression were elevated, while PRIM1 and LYAR expression levels were significantly reduced." (PMID 40799650, 2025).
endometrial cancer (1 paper, 2025). Primary or metastatic malignant neoplasm involving the endometrium (mucous membrane that lines the endometrial cavity). "The association between RCOR2 expression and poor prognosis in endometrial cancer patients is consistent with studies on other transcriptional regulators in cancer." (PMID 40936699, 2025). "The study’s primary focus was on pathological differences between tumor and adjacent normal tissues, with RCOR2 found to be significantly overexpressed in endometrial cancer and associated with adverse clinicopathological features, including stage, grade, and lymph node metastasis." (PMID 40936699, 2025). "Correlation analysis showed that all three genes, MKI67, CCND1, and PCNA, exhibited a significant positive correlation with RCOR2 mRNA expression in endometrial cancer tissues." (PMID 40936699, 2025). "Functional assays revealed that RCOR2 knockdown suppressed, while overexpression promoted, proliferation of endometrial cancer cells." (PMID 40936699, 2025). "The impact of RCOR2 overexpression and inhibition on endometrial cancer cell proliferation was further evaluated by using colony formation assay." (PMID 40936699, 2025). "Thus, the key conclusion regarding RCOR2 overexpression in endometrial cancer and its clinical relevance remains robust." (PMID 40936699, 2025). "The overexpression of RCOR2 in endometrial cancer tissues and its correlation with advanced clinical stages, higher histological grades, and lymph node metastasis suggest that RCOR2 may drive tumor progression through various molecular pathways." (PMID 40936699, 2025). "Mechanistically, RCOR2 has been implicated in transcriptional repression networks involving REST and HDACs, and may influence endometrial cancer progression by modulating epigenetic landscapes that control proliferation and differentiation pathways." (PMID 40936699, 2025). "RCOR2 mRNA expression and clinicopathological factors in endometrial cancer patients (n = 174)." (PMID 40936699, 2025). "Furthermore, WB showed that RCOR2 knockdown or overexpression could change the expression of MKI67, CCND1, and PCNA in endometrial cancer cells remarkedly, which further demonstrated at the protein level that RCOR2 the proliferation of endometrial cancer cells." (PMID 40936699, 2025). "Next, we analyzed the relationship between RCOR2 and the proliferation-related genes MKI67, CCND1, and PCNA under the mRNA levels, in endometrial cancer." (PMID 40936699, 2025).
ependymoma (1 paper, 2023). A WHO grade II, slow growing tumor of children and young adults, usually located intraventricularly. "To validate the relevance of RCOR2 for ependymoma cell growth, we performed shRNA-mediated knock-down of RCOR2 expression in patient derived ZFTA and PFA cell lines." (PMID 37085539, 2023). "Since there is no available compound against RCOR2, we reasoned that inhibition of other components of the RCOR2/LSD1/HDAC complex may confer a therapeutic vulnerability for ZFTA ependymoma." (PMID 37085539, 2023). "In addition, LSD1 and RCOR2 transcription are strongly correlated in ZFTA but not in PFA ependymomas." (PMID 37085539, 2023). "Here, we have shown that both RCOR2 and LSD1 expression are essential in ZFTA ependymoma, but not or to a lesser extent in PFA ependymoma, and that ZFTA cells are sensitive to HDAC1/2 inhibitors in line with our previous observations." (PMID 37085539, 2023).
glioma (1 paper, 2014). A benign or malignant brain and spinal cord tumor that arises from glial cells (astrocytes, oligodendrocytes, ependymal cells). "A negative correlation between Rcor2 and Il6 gene expression was also verified in LPS-treated C6 glioma cells." (PMID 25051986, 2014).
lymph node metastasis (1 paper, 2025). "It was observed that RCOR2 expression was significantly associated with clinical stage, histologic grade, and lymph node metastasis." (PMID 40936699, 2025). "High RCOR2 expression correlated with advanced clinical stage, high histologic grade, and lymph node metastasis." (PMID 40936699, 2025). "The results show a significant correlation between RCOR2 mRNA expression and clinical stage, histologic grade, and lymph node metastasis." (PMID 40936699, 2025). "Specifically, we compared RCOR2 mRNA expression levels in tumor tissues between patients with clinical stages I-II and III-IV, with and without lymph node metastasis, and histologic grades G1-G2 and G3." (PMID 40936699, 2025).
melanoma (1 paper, 2025). A malignant, usually aggressive tumor composed of atypical, neoplastic melanocytes. "We show that RCOR2 is negatively associated with anti–PD-1 therapy in melanoma patients." (PMID 40608411, 2025). "The transcriptomic analysis revealed a significant decrease in RCOR2 mRNA expression in melanoma from patients who achieved a partial or complete response to anti–PD-1 ICB, as compared with those who did not respond to the treatment." (PMID 40608411, 2025). "The highest levels of RCOR2 mRNA were detected in 13 non-responding melanoma tumors, whereas the lowest levels of RCOR2 mRNA were found in 5 completely responding melanoma tumors." (PMID 40608411, 2025).
tumor (8 papers, 2020 to 2025). "Loss of RCOR2 significantly enhances anti–PD-1 therapeutic efficacy in both immune-hot and -cold tumor models." (PMID 40608411, 2025). "Reduced tumor initiation frequency by RCOR2 loss in mice was also rescued when RNF43 was co-deleted." (PMID 40608411, 2025). "The diagnostic value of RCOR2 was further confirmed by ROC analysis, which demonstrated strong sensitivity and specificity for distinguishing tumor aggressiveness, making RCOR2 a candidate diagnostic biomarker." (PMID 40936699, 2025). "MHC-II protein depletion completely abolished tumor reduction caused by RCOR2 loss in mice, which phenocopied CIITA loss." (PMID 40608411, 2025). "Genes and gene subsets identified in this study may function to facilitate tumor immune evasion, as evidenced by confirmatory phenotypic observations associated with RCOR2 and BMP7 expression." (PMID 32117236, 2020). "To determine whether loss of CD4+ and/or CD8+ T cells is necessary for RCOR2-mediated tumor growth, we administered anti-CD4 antibody, anti-CD8 antibody, anti-CD4/CD8 antibodies or control antibody isotype intraperitoneally into tumor-bearing mice to deplete CD4+ and CD8+ T cells." (PMID 40608411, 2025). "Based on the mRNA expression level of RCOR2, tumor tissues were categorized into low and high expression groups." (PMID 40936699, 2025). "Our studies suggest that RNF43 silencing by RCOR2 is an additional mechanism to diminish its tumor suppressor function in wild-type tumors." (PMID 40608411, 2025). "In this study, we uncover a dual role of the RCOR2 complex in tumor cell plasticity and immunogenicity leading to tumor initiation and progression in mice." (PMID 40608411, 2025). "RCOR2 was upregulated predominantly in tumor cells and promoted tumor development in mice through reducing tumor cell death by CD4+CD8+ T cells and inducing cancer stemness." (PMID 40608411, 2025). "Here, we showed that the transcriptional corepressor RCOR2 is a key factor that integrates two epigenetic programs surveilling tumor plasticity and immunogenicity." (PMID 40608411, 2025). "Collectively, our work identifies a “two birds with one stone” effect for RCOR2 in cancers and establishes a valuable framework to simultaneously target tumor cell plasticity and immunogenicity for the better treatment of human cancers." (PMID 40608411, 2025). "Homozygous deletion of Rcor2 significantly decreased incidence and numbers of murine PyMT tumors in mice, indicating that RCOR2 promotes tumor initiation." (PMID 40608411, 2025). "In this study, we showed that RCOR2 was upregulated predominantly in tumor cells and promoted tumor development by simultaneously increasing tumor cell plasticity and immune evasion." (PMID 40608411, 2025). "While our findings establish a strong link between RCOR2 expression and tumor behavior, the precise molecular mechanisms by which RCOR2 modulates transcription in UCEC remain to be elucidated." (PMID 40936699, 2025). "Collectively, these results indicate that RCOR2 enhances cancer cell plasticity to promote tumor development." (PMID 40608411, 2025). "Collectively, our studies suggest that targeting RCOR2 can inhibit not only tumor plasticity but also immune evasion, potentially eradicating malignant diseases and substantially advancing cancer treatment." (PMID 40608411, 2025). "An enhanced tumor-inhibitory effect of anti–PD-1 antibody and RCOR2 KO1 combination was also achieved in the MC38 mouse model." (PMID 40608411, 2025). "Intriguingly, we found widespread upregulation of RCOR2 mRNA in various types of human cancers in The Cancer Genome Atlas (TCGA) cohort, predominantly expressed in malignant tumor cells." (PMID 40608411, 2025). "To determine the mechanism by which tumoral RCOR2 promotes tumor cell plasticity and immune evasion, we assessed RCOR2 transcriptome in MDA-MB-231 cells by RNA sequencing (RNA-Seq)." (PMID 40608411, 2025).
tumor (continued). "Collectively, these results indicate that RCOR2 promotes tumor growth through reducing infiltration of CD4+ and CD8+ T cells." (PMID 40608411, 2025). "Thus, targeting RCOR2 is a valuable therapeutic strategy that can achieve selective tumor cell death with less immunotoxicity to normal tissues." (PMID 40608411, 2025). "RCOR2 KO1 or KO2 significantly decreased the tumor incidence in NSG mice." (PMID 40608411, 2025). "Tumoral CIITA/MHC-II silencing is responsible for RCOR2-induced tumor immune evasion." (PMID 40608411, 2025). "Tumoral RCOR2 inhibits cytotoxic T cell infiltration to promote tumor growth in mice." (PMID 40608411, 2025). "Activation of Wnt/β-catenin signaling is responsible for RCOR2-induced tumor cell plasticity." (PMID 40608411, 2025). "To determine whether RCOR2 controls tumor cell plasticity to promote tumor development, we performed limiting dilution assay in NSG mice." (PMID 40608411, 2025). "These insights raise the possibility that RCOR2, through its association with LSD1/CoREST complexes, may contribute to the silencing of tumor suppressor genes or the activation of oncogenic enhancers." (PMID 40936699, 2025). "RCOR2 is upregulated primarily in tumor cells across human cancers." (PMID 40608411, 2025). "Given that tumor-related epigenetic dysregulation and abnormal cell proliferation likely exert stronger effects on RCOR2 expression than physiological hormonal changes, and considering the paired tissue design from the same patients, potential confounding from menstrual cycle phases is minimal." (PMID 40936699, 2025). "Notably, RCOR2 KO significantly inhibited MDA-MB-231 tumor growth in NSG mice when a limited number of cancer cells were implanted." (PMID 40608411, 2025). "Similarly, we detect increased IFN-γ, TNF-α, and IL-2 expression in CD4+ T cells after coculture with RCOR2-KO tumor cells." (PMID 40608411, 2025). "RCOR2 increases intrinsic cancer cell plasticity to promote tumor development in mice." (PMID 40608411, 2025). "Next, we studied whether CIITA silencing regulates RCOR2-induced tumor immune evasion." (PMID 40608411, 2025). "The RCOR2/LSD1 sub-axis suppresses RNF43 transcription to activate Wnt/β-catenin signaling in tumor cells, whereas the RCOR2/HDAC1/2 sub-axis inhibits CIITA and MHC-II expression in tumor cells to block activation of CD4+ and CD8+ T cells." (PMID 40608411, 2025). "CIITA KO counteracted RCOR2 KO1–induced MHC-II molecules in TUBO and MC38 cells, suggesting that RCOR2 indirectly reduces MHC-II expression in tumor cells by repressing CIITA." (PMID 40608411, 2025). "RCOR2 hijacked LSD1- and HDAC1/2-dependent epigenetic programs to promote tumor plasticity and immune evasion, respectively." (PMID 40608411, 2025). "Given its selective expression pattern in tumor cells, RCOR2 is a specific corepressor of CIITA and MHC-II in tumor cells." (PMID 40608411, 2025). "Mechanistically, RCOR2 repressed RNF43 expression through LSD1-mediated demethylation of histone H3 at lysine 4 to induce activation of Wnt/β-catenin and tumor stemness." (PMID 40608411, 2025). "Simultaneously, RCOR2 inhibited CIITA expression through HDAC1/2-mediated deacetylation of histone H4 at lysine 16, leading to MHC-II silencing in tumor cells and subsequent impairment of CD4+CD8+ T cell immunosurveillance, thereby promoting immune evasion." (PMID 40608411, 2025). "Collectively, these findings indicate that RCOR2 downregulates MHC-II–mediated antigen presentation in cancer cells, leading to tumor escape from T cell immunosurveillance." (PMID 40608411, 2025). "By computational reconstruction of the tumor genome, we observed the formation of neo-TADs in all ZFTA samples, placing the REST Corepressor 2 (RCOR2) gene in new regulatory environments." (PMID 37085539, 2023). "This study provides the first comprehensive evidence that RCOR2 plays an oncogenic role in UCEC, particularly by regulating tumor cell proliferation, and may serve as a novel biomarker and therapeutic target." (PMID 40936699, 2025).